CCL22 (C-C motif chemokine ligand 22)
Description:
May play a role in the trafficking of activated/effector T-lymphocytes to inflammatory sites and other aspects of activated T-lymphocyte physiology. Chemotactic for monocytes, dendritic cells and natural killer cells. Mild chemoattractant for primary activated T-lymphocytes and a potent chemoattractant for chronically activated T-lymphocytes but has no chemoattractant activity for neutrophils, eosinophils, and resting T-lymphocytes. Binds to CCR4. Processed forms MDC(3-69), MDC(5-69) and MDC(7-69) seem not be active.
Synonyms: MDC; SCYA22; A-152E5.1; STCP-1; ABCD-1; DC/B-CK; MGC34554
Tractability: Antibody: its Gene Ontology location is reachable by antibodies, with high confidence; UniProt places it where antibodies can reach, with medium confidence; UniProt predicts a signal peptide or a membrane-spanning region.
Target class: Secreted protein
Gene: Protein-coding gene on chromosome 16 (57,357,925 to 57,366,191, forward strand). Ensembl gene ENSG00000102962.
Subcellular location: Secreted
Pathways (Reactome):
Immune System: Dectin-1 mediated noncanonical NF-kB signaling; Interleukin-10 signaling; Interleukin-4 and Interleukin-13 signaling
Signal Transduction: Chemokine receptors bind chemokines
Gene Ontology:
Molecular function: protein binding; CCR chemokine receptor binding; chemokine activity
Biological process: antimicrobial humoral immune response mediated by antimicrobial peptide; cell chemotaxis; cell-cell signaling; chemokine-mediated signaling pathway; chemotaxis; eosinophil chemotaxis; immune response; inflammatory response; positive regulation of cell migration; response to virus; signal transduction
Cellular component: extracellular region
Genetic constraint (gnomAD): Loss-of-function variants: 6 observed, 6.97 expected, observed/expected ratio (o/e) 0.86, 90% interval 0.47 to 1.63. That is too few expected variants to judge how well the gene tolerates losing a copy. Missense variants: 91 observed, 95.27 expected, observed/expected ratio (o/e) 0.96, 90% interval 0.81 to 1.14. Synonymous variants: 43 observed, 37.38 expected, observed/expected ratio (o/e) 1.15, 90% interval 0.9 to 1.48.
Homologues: Orthologues: chimpanzee CCL22 (98% identical), macaque CCL22 (90% identical), pig CCL22 (76% identical), guinea pig CCL22 (72% identical), rabbit CCL22 (72% identical), dog CCL22 (70% identical), rat Ccl22 (65% identical), mouse Ccl22 (62% identical), zebrafish ccl38a.4 (23% identical), zebrafish ccl38a.5 (22% identical), zebrafish ccl38.1 (20% identical), zebrafish ccl38.6 (17% identical). Paralogues in human: CCL17 (35% identical), CCL4 (34% identical), CCL18 (32% identical), CCL4L2 (32% identical), CCL1 (31% identical), CCL5 (31% identical), CCL7 (31% identical), CCL11 (30% identical), CCL26 (30% identical), CCL3 (30% identical), CCL3L3 (30% identical), CCL13 (29% identical), and 14 more.
Diseases named in the same sentence as CCL22 in open-access papers:
CCL22 is named in the same sentence as 243 diseases in open-access papers, as found by Europe PMC text mining. Sharing a sentence is not in itself a finding about the gene and the disease. The quoted sentences say what the papers report.
breast carcinoma (39 papers, 2011 to 2025). "As such, CCL22 has been described as a pro-malignant cytokine, and high serum levels of CCL22 were associated with advanced stage of disease as well as an impaired prognosis in patients with gastric cancer and breast cancer." (PMID 29899223, 2018). "The CCR4 (receptor of CCL17 and CCL22) expression level in breast cancer was reported to be associated with lung metastasis." (PMID 28039457, 2017). "CCL5 and CCL22 are strongly associated with the progression of breast cancer." (PMID 34602068, 2021). "Elevated serum CCL22 was also linked with improved survival in a cohort of 1208 patients with glioma; however, serum CCL22 was found to be elevated in advanced tumor stages in breast cancer and was associated with metastatic spread and recurrence in gastric cancer patients." (PMID 33202734, 2020). "In breast cancer, tumour‐derived chemokines such as CCL22 and CCL1 bind to CCR4 and CCR8 on Tregs, guiding their migration into tumour tissues." (PMID 41200753, 2025). "The mean serum levels of chemokine CCL22 were significantly higher in breast cancer patients than in healthy individuals." (PMID 39003350, 2024). "While, after adjusting for comorbidities (obesity, T2D, and HTN), breast cancer, age, smoking, and alcohol consumption, MDC/CCL22, VEGFα, and Groα remained significantly associated with AA." (PMID 38541912, 2024). "Recently, it has been reported that other immune cells such as monocytes and T-cells as well as epithelial cells and several cancer cells, i.e. breast cancer cells, express CCL22." (PMID 39232378, 2024). "This is in line with other studies on ovarian and breast cancer and indicates the potential Treg-recruitment via CCL22." (PMID 39232378, 2024). "Increased concentrations of MDC/CCL22 in transformed tissues has been shown to lead to T regulatory cells infiltration in melanoma as well as ovarian, prostate, or breast carcinomas." (PMID 37685890, 2023). "CCL22 production by tumor cells was identified as a mechanism of immune escape in breast cancer, through CCR4+ Treg recruitment in the tumor microenvironment (TME), induced by IFNγ exposure." (PMID 35794623, 2022). "Many studies have shown that CCL17 and CCL22 are highly expressed in various tumor tissues including lung cancer, colorectal cancer, gastric cancer, breast cancer, and ovarian cancer." (PMID 34885241, 2021). "We have recently described expression of the classic Treg-attracting chemokine CCL22 in breast cancers." (PMID 30572845, 2018). "The aim of this study was to identify the role of the two major Treg-attracting chemokines CCL1 and CCL22 in human breast cancer." (PMID 30572845, 2018). "Similar to intratumoral Treg infiltrates, CCL22 tumor secretion correlated with the prognosis of the molecular subtypes of breast carcinoma (P<0.0001)." (PMID 24124553, 2013). "A few studies have indicated that CCL22 secreted by solid tumor cells is responsible for accumulation of Foxp3 +Tregs in ovarian, prostate, gastric, esophageal, and breast carcinomas." (PMID 24124553, 2013). "Some studies describe CCL22 as being exclusively expressed by immune cells like macrophages and DC, while others report an expression also by tumor cells, like in oral squamous cell carcinoma and breast cancer." (PMID 39232378, 2024). "It was also shown that the CCL22 serum levels increases with advancing tumor stages, indicating that the elevated levels of CCL22 may contribute to breast cancer progression and development." (PMID 39003350, 2024). "Additionally, in breast cancer CCL22 is known to influence the recruitment of regulatory T cells to areas of immune cell infiltrates." (PMID 36717913, 2023). "The regulatory T cells (Tregs) can be attracted by CCL22 into the tumor microenvironment, to reduce anti-cancer immunity, which are widely expressed in many cancers, including glioma, gastric cancer, and breast cancer." (PMID 35176085, 2022). "Both CCL1 and CCL22 were expressed in most breast cancer tissues." (PMID 30572845, 2018).
breast carcinoma (continued). "Likewise, high expression of CCL22 in breast cancer is related to a higher Treg infiltration and reduced prognosis." (PMID 30572845, 2018). "We found CCL1, CCL22, and FoxP3 expressing cells in most breast cancer tissues analyzed." (PMID 30572845, 2018). "Several of them like CCL22, four and a half LIM domains protein 1 (FHL1) and leukemia inhibiting factor (LIF) were detected in the breast CAAT proteome and have been linked with breast cancer proliferation and growth." (PMID 28525384, 2017). "Elevated CCL22 expression is associated with increased Treg recruitment into primary DCIS and IDC lesions, suggesting that Tregs may contribute to early breast cancer immunosuppression." (PMID 23408142, 2013). "After being cultured with breast cancer MDA-MB-453 cell-conditioned medium, macrophages were inclined to the M2 phenotype (IL-10 high, TGF-β high, CD163 high, CCL-17 high, CCL-22 high) in the circWWC3-transfected group as compared to the control group." (PMID 35996149, 2022). "Except for CCL19, RAET1G, IL12B, CXCL13, CCL22, and NOS1 were significantly highly expressed in breast cancer at the mRNA level." (PMID 36292723, 2022). "Consistently, it has been reported that the increased expression of CCL17 and CCL22 correlates with the infiltration of CCR4-expressing Treg cells and poor clinical outcomes in gastric cancer, breast cancer, and oral tongue squamous cell carcinoma." (PMID 34885241, 2021). "This study demonstrates that oestrogen deprivation increases breast cancer secretion of TNF, CCL5, IL-6, IL-8, and CCL22 and alters total human peripheral blood mononuclear cell migration in an in vitro assay." (PMID 34602068, 2021). "In order to determine the role of CCL1 and CCL22 on Treg attraction to breast cancer, we analyzed 199 breast cancer tissue samples that were previously stained for expression of CCL1, CCL22 and FoxP3." (PMID 30572845, 2018). "We stained tissue microarrays (TMA) of 199 breast cancer patients for expression of CCL1, CCL22 and FoxP3." (PMID 30572845, 2018). "In order to investigate the role of CCL1 and CCL22 on Treg infiltration and overall survival in breast cancer patients, we stained tissue microarrays of 199 breast cancer patients for the CCL1, CCL22 and FoxP3." (PMID 30572845, 2018). "Chemokines with well-known functions in mammary cancer include CCL2, CCL5, CCL19, CCL20, CCL21 and CCL22." (PMID 30572845, 2018). "CCL22, for example, is only present at concentrations up to 1 ng/mL in ascites and tissue samples of ovarian cancer, as are CCL2 levels in the plasma of breast cancer patients." (PMID 36834542, 2023). "The same mechanism might apply within breast cancer patients with high tumor grade, with an abundance of apoptotic cells or necrotic cells, thus recruiting CD169+ TAMs which release CCL22 and recruit Tregs." (PMID 36831605, 2023). "After the occurrence of tumour metastasis, breast cancer cells could stimulate lung tissue to secrete CCL17 and CCL22, which attract CCR4-positive Treg cells to accumulate in lung tissue, and thus facilitating lung metastasis of breast cancer." (PMID 36569832, 2022). "To assess the effect of oestrogen deprivation on chemokine gene expression in ER+ MCF-7 breast cancer cells, we used RT-qPCR to measure the mRNA expression of chemokines CCL5, CCL22, and CXCL16 from nine biological replicates from three independent experiments." (PMID 34602068, 2021). "ABCA3, CCL22, FOXJ1, IL1RN, and MAP2K6 may serve as good prognostic factors, while KCNIP3 and MRPL13 may be poor prognostic factors for the prognosis of breast cancer." (PMID 32977823, 2020). "Combined with our results, it was speculated that CCL22, FOXJ1, and IL1RN may play an important role in ameliorating the prognosis of breast cancer patients through involving in immune response." (PMID 32977823, 2020).
breast carcinoma (continued). "As shown in breast cancer research studies, these cells in the tumor niche express CCR8 (receptor for CCL1/I-309) and CCR4 (receptor for CCL17/thymus and activation regulated chemokine (TARC) and CCL22/macrophage derived chemokine (MDC))." (PMID 33114763, 2020). "Surprisingly, our data showed upregulation of CCL1 in breast cancer tissues, whereas CCL22 expression was not elevated when compared to normal breast tissue and did not correlate with Treg infiltration." (PMID 30572845, 2018). "Although CCL22 has been best described in the context of Treg recruitment to cancer, CCL22 levels were not significantly increased in our breast cancer tissue cohort." (PMID 30572845, 2018). "CCL1 was highly upregulated in breast cancer, positively correlated with Treg infiltration and high grade tumors, whereas none of these was found for CCL22." (PMID 30572845, 2018). "Breast cancer cells secrete CCL17 and CCL22, which recruit CCR4-expressing Treg and Th2 cells." (PMID 23408142, 2013). "Recent studies on breast cancers have shown that two of these chemokines, CCL20 and CCL22, may recruit Treg that express the corresponding chemokine receptors CCR6 and CCR4." (PMID 21521526, 2011). "In breast cancer, CCL22 has been shown to be chemoattractive for CCR4+, but not CCR4- T-reg." (PMID 37063842, 2023). "Biomarkers including FOXJ1, CCL22, ABCA3 and IL1RN may be good prognostic factors in breast cancer." (PMID 36397112, 2022). "In conclusion, ABCA3, CCL22, FOXJ1, MAP2K6, and IL1RN may serve as good prognostic factors, while KCNIP3 and MRPL13 may be poor prognostic biomarkers to predict the recurrence and prognosis of breast cancer." (PMID 32977823, 2020). "However, CCL22 and CCL28 expression is not increased in human breast cancers compared to normal breast tissue, making them unlikely Treg recruiters to human breast cancer." (PMID 28290464, 2017). "Significant changes in CCL22 and CCL28 in the online breast cancer data sets also showed decreased tumor expression, suggesting that these chemokines are unlikely to play an important role in Treg recruitment to breast cancer." (PMID 28290464, 2017). "Thus, in breast cancer, CCL1 rather than CCL22 seems to impact Treg migration and could affect patient survival." (PMID 30572845, 2018).
asthma (35 papers, 2011 to 2025). "In the allergic group, we observed a positive association of CCL22 and IL-1RA with adult-onset asthma." (PMID 31217483, 2019). "In conclusion, low mother-to-child Th2-associated chemokine CCL22 levels appear to be inversely related to mite sensitization and the risk of asthma development in early childhood." (PMID 29662241, 2018). "A lower CCL22 level at birth with a slight rise during infancy was associated with higher prevalence of mite sensitization and a higher risk of asthma at 3 years-of-age (P = 0.014)." (PMID 29662241, 2018). "Increased circulating levels of Th2-associated chemokine CCL22 are reportedly associated with allergic symptoms, including atopic dermatitis and asthma." (PMID 27863395, 2017). "However, an inverse association between cord blood CCL22 levels and allergic sensitization risk in asthma suggests that the antibodies to allergens of maternal influences may induce tolerance and protection from allergic asthma in early childhood." (PMID 29662241, 2018). "The role of C–C motif chemokine ligand (CCL) 17 and CCL22 signalling has been demonstrated in allergic disorders, such as asthma and atopic dermatitis, as well as multiple types of neoplastic disorders." (PMID 41291326, 2025). "The differentially expressed genes included those related to inflammation (CCL22, CXCL16, AREG, MMP12) involved in asthma pathophysiology, as well as genes associated with the skin barrier (IVL, CDSN, SPINK5, FLG)." (PMID 39451560, 2024). "Clinical significance of combined detection of CCL22 and IL‐1 as potential new bronchial inflammatory mediators in children asthma." (PMID 39508721, 2024). "CCL17 and CCL22 have been studied as potential therapeutic targets for type 2 inflammatory diseases, including asthma." (PMID 39508721, 2024). "Our findings indicate that CCL22 and IL‐1 levels were significantly elevated in both acute and stable asthma groups compared to the control group." (PMID 39508721, 2024). "Our results show that CCL22 and IL‐1 are both representative markers during asthma symptom exacerbations and an immune mediator that can predict response to azithromycin therapy." (PMID 39508721, 2024). "CCL22 and IL‐1 were found to be significantly up‐ or downregulated during acute and stable asthma attacks." (PMID 39508721, 2024). "In conclusion, our findings indicate that CCL22 and IL‐1 levels are markedly higher in acute asthma compared to stable asthma and also an immune mediator that can predict response to azithromycin therapy." (PMID 39508721, 2024). "Total serum IgE and the levels of BALF Th2 cytokines/chemokines such as CCL17, CCL22, IL-13, IL-17, and periostin were elevated in the severe asthma mice compared to the saline-treated control." (PMID 35958610, 2022). "Our study shows that plasma concentrations of IL-1RA, EGF, and CCL22 were elevated in asthma patients compared to the control group." (PMID 31217483, 2019). "In this study, a lower CCL22 level at birth (<500 pg/mL) with a slight rise during infancy was related to higher prevalence of mite sensitization and asthma later in life." (PMID 29662241, 2018). "Multiple logistic regression analysis revealed that children with a slight rise in CCL22 levels in cluster C were more likely to suffer from asthma at 3 years-of-age (odds ratio, 6.46; 95% confidence interval, 1.45–28.78; P = 0.014)." (PMID 29662241, 2018). "The importance of CCL17 and CCL22 is furthermore confirmed in murine asthma models where their neutralization with specific antibodies resulted in attenuation of AHR and airway inflammation." (PMID 28894452, 2017). "Previous studies have found that CCL22 also plays an important role in asthma." (PMID 39508721, 2024). "In our study, we also found that CCL22 and IL‐1 may serve as independent predictors of acute asthma." (PMID 39508721, 2024). "Our findings indicate that CCL22 and IL‐1 levels were higher in acute asthma than in stable asthma." (PMID 39508721, 2024).